FGF23 (fibroblast growth factor 23)
Diseases named in the same sentence as FGF23 in open-access papers (continued):
Sharing a sentence is not in itself a finding about the gene and the disease.
autosomal dominant hypophosphatemic rickets (continued). "Autosomal dominant hypophosphatemic rickets, described in 1971,8 occurs because of mutations in the gene of FGF23 in chromosome 12p13, withgain in function, resulting in high levels of FGF23." (PMID 29617471, 2018). "FGF23 was first identified as the phosphaturic substance when mutations in FGF23 were linked to autosomal-dominant hypophosphatemic rickets (ADHR)." (PMID 26744291, 2016). "Recent studies have implicated the hypoxia-inducible factor-1α (HIF-1α) in other phosphate wasting disorders caused by elevated FGF23, including X-linked hypophosphatemic rickets and autosomal dominant hypophosphatemia." (PMID 27468359, 2016). "Other possible causes of renal phosphate wasting with elevated FGF23 levels include inherited hypophosphatemic osteomalacia such as X-linked hypophosphatemic rickets, autosomal dominant hypophosphatemic rickets and autosomal recessive hypophosphatemic rickets." (PMID 27709474, 2016). "Activating mutations in the gene for FGF23 cause autosomal dominant hypophosphatemic rickets (ADHR; OMIM #193100), which is characterized by renal Pi wasting, hypophosphatamia, and an inappropriately low level of serum 1,25(OH)2D." (PMID 24710520, 2014). "Autosomal dominant hypophosphatemic rickets (ADHR) is caused by mutations in FGF23 gene." (PMID 33191899, 2021). "An autosomal dominant inheritance pattern causing disease in offspring of either gender should raise the possibility of autosomal dominant hypophosphatemic rickets (mutation in the FGF23 gene) or vitamin D–dependent rickets type III (mutation in the CYP3A4 gene)." (PMID 33660084, 2021). "In 2000, FGF23 was ultimately identified in the ventrolateral thalamic nucleus of mice, and its biological significance rapidly followed when a missense mutation of the Fgf23 gene in patients with autosomal dominant hypophosphatemic rickets (ADHR) was identified thereafter." (PMID 31461904, 2019). "Autosomal dominant hypophosphatemic rickets (ADHR) is due to mutations rendering FGF23 resistant to cleavage." (PMID 35084563, 2022). "Over 20 years ago, genetic mutations in the FGF23 gene were identified as the cause of autosomal dominant hypophosphatemic rickets (ADHR)." (PMID 32857288, 2020). "FGF23 was discovered as a novel member of theFGF family in the year 2000, when mutations putatively interfering with cleavage of theprotein were identified as the cause of autosomal dominant hypophosphatemic rickets (ADHRs),an inherited renal phosphate-wasting disease." (PMID 29096595, 2017). "This condition includes several forms: autosomal dominant hypophosphatemic rickets (ADHR) caused by FGF23 mutations, autosomal recessive hypophosphatemic rickets (ARHR) caused by DMP1 mutations, and X‐linked hypophosphatemic rickets (XLH) caused by PHEX mutations." (PMID 40661139, 2025). "In autosomal dominant hypophosphatemic rickets (ADHR), a mutation at the cleavage site abolishes cleavage of FGF23, resulting in a higher concentration of iFGF23 in the body, leading to phosphate wasting." (PMID 39766329, 2024). "Fibroblast growth factor-23 (FGF23) was discovered as markedly elevated ‘phosphatonin’ in patients with autosomal dominant hypophosphatemic rickets." (PMID 37992803, 2023). "FGF23 was initially identified in studies on autosomal dominant hypophosphatemic rickets (ADHR), in which mutations in the FGF23 gene lead to excessive serum FGF23 concentration by preventing cleavage of the active intact FGF23 (iFGF23) into inactive N-terminal and C-terminal FGF23 (cFGF23)." (PMID 37284066, 2023). "Autosomal-dominant hypophosphatemic rickets (ADHR) is a rare disorder, due to activating pathogenic variants of the FGF23 gene." (PMID 34910242, 2022). "For example, the FGF23 gene with a gain of function mutations may cause autosomal dominant hypophosphatemic rickets (ADHR)." (PMID 34572066, 2021).
autosomal dominant hypophosphatemic rickets (continued). "The marked increase in FGF23 during CKD goes beyond phosphate, as it was demonstrated in a mouse model of autosomal dominant hypophosphatemic rickets (ADHR) that iFGF23 was elevated during iron‐deficiency anemia in the genetic background of an Fgf23 stabilizing mutation." (PMID 32476270, 2020). "The key molecular mechanism involves excess fibroblast growth factor 23 (FGF23) production, a phosphatonin first identified in autosomal dominant hypophosphatemic rickets and tumor-induced osteomalacia." (PMID 31730177, 2020). "Within a year of its discovery, it was found that excess FGF23 is responsible for the occurrence of many diseases with renal phosphate wasting, including autosomal dominant hypophosphatemic rickets (ADHR), in which pathogenic variants of the FGF23 gene have been identified." (PMID 41008628, 2025). "Fibroblast growth factor 23 (FGF23) was identified as a responsible gene for autosomal dominant hypophosphatemic rickets (ADHR) in 2000 by positional cloning." (PMID 29515522, 2018). "Indeed, FGF23 is an etiology factor of autosomal dominant hypophosphatemic rickets (ADHR) and tumor-induced osteomalacia." (PMID 27867811, 2016). "FGF23 was initially reported as a gene responsible for autosomal-dominant hypophosphatemic rickets, and was found to be also elevated in the serum of patients with TIO, thus making measurement of serum FGF23 helpful in the differential diagnosis of hypophosphatemic diseases." (PMID 36686800, 2022). "High levels of FGF23 could also occur in Autosomal Dominant Hypophosphatemic Rickets (ADHR), which is caused by the inactive mutation in the proteolytic cleavage domain (RXXR cleavage motif) in FGF23, therefore the variation renders FGF23 resistant to proteolytic cleavage." (PMID 33015068, 2020). "It was in the hypophosphatemic disorders, autosomal dominant hypophosphatemic rickets (ADHR) and tumor induced osteomalacia (TIO), that FGF23 first was identified and its role in phosphate metabolism recognized." (PMID 24373521, 2013).
hyperparathyroidism (86 papers, 2012 to 2026). Hyperfunction of the parathyroid glands resulting in the overproduction of parathyroid hormone. "In case of TIO and concomitant hyperparathyroidism, which occurred in the described case, the phosphate-lowering effect of FGF-23 was enhanced by PTH action causing high bone turnover and progressive bone loss." (PMID 35090436, 2022). "Phosphate supplementation may exacerbate hyperparathyroidism, increase FGF-23 levels, and even cause nephrocalcinosis, and thus research into the effects of supplementation in asymptomatic mild-to-moderate hypophosphataemia is also required." (PMID 34886802, 2021). "If PTH alters the effect of FGF23 excess, then the magnitude of the causal effect of FGF23 on TmP/GFR could be lessened by hypoparathyroidism or it could be augmented by hyperparathyroidism." (PMID 33615106, 2021). "However, our model reproduces the real-life condition, where a HiP diet is usually associated with hyperparathyroidism and high levels of FGF-23." (PMID 34357974, 2021). "Furthermore, a rare disease termed Hypophosphatemic Rickets with Hyperparathyroidism caused by a balanced translocation adjacent to the KL gene, whose product is FGF23’s necessary cofactor alpha-Klotho, could lead to an increase of circulating alpha-Klotho." (PMID 33015068, 2020). "XLH treatments include oral phosphate and active vitamin D—which are associated with a burdensome dosing regimen, gastrointestinal disturbances, hyperparathyroidism, and nephrocalcinosis—or burosumab, a fully human anti-FGF23 antibody." (PMID 40260280, 2025). "In patients with end-stage HF, hyperparathyroidism and markedly elevated c-terminal FGF23 levels were reported, with 98.7% of FGF23 values above the reference range." (PMID 40565034, 2025). "In CKD, a state of hyperparathyroidism develops despite the increased and possibly inhibitory effect of FGF23." (PMID 38732094, 2024). "Disordered mineral bone metabolism with respect to serum phosphate, serum FGF-23, hyperparathyroidism, and bone densitometry Z-score was evident with advancing CKD stages." (PMID 36873652, 2023). "Even following transplantation, sclerostin eventually begins to rise in the case of hyperparathyroidism, along with FGF-23, uremic toxins, and various inflammatory cytokines." (PMID 37836411, 2023). "PTH also stimulates the production of FGF23, as suggested by the elevated serum levels of FGF23 in patients and mouse models of hyperparathyroidism." (PMID 35909535, 2022). "The parathyroid gland is one of the target organs of FGF23, mice that overexpressing FGF23 will get hyperparathyroidism." (PMID 34901023, 2021). "For those who have never received phosphate therapy, a reduced circulating level of 1,25(OH)2D due to excess FGF-23 is very likely the main factor involved in the development of hyperparathyroidism." (PMID 34141703, 2021). "While phosphate availability increases, FGF23 levels are further increased by treatment and serious side effects such as hyperparathyroidism and nephrocalcinosis occur frequently." (PMID 31993875, 2020). "In the literature, increased levels of serum phosphorus and FGF23 levels have been linked to unexpected outcomes such as CKD, hyperparathyroidism, and cardiovascular events in humans." (PMID 32116791, 2020). "It has been also revealed that FGF23 concentrations can be significant predictor of refractory hyperparathyroidism." (PMID 28497083, 2017). "In dialysis patients with hyperparathyroidism, FGF23 level was more predictive of successful treatment with calcitriol to lower parathormone." (PMID 28497083, 2017). "Although in CKD administration of vitamin D or active vitamin D may increase circulating calcitriol and may thus reduce hyperparathyroidism, this can also increase intestinal P absorption rate and FGF23." (PMID 40565034, 2025).
hyperparathyroidism (continued). "Therefore, it appears to be likely that the effect of enhanced chemerin production on FGF23 in CKD is overridden by various other stimulating effects on FGF23 associated with CKD, e.g. phosphate overload, inflammation, hyperparathyroidism." (PMID 39887469, 2025). "The FGF23‐mediated effect of suppressing renal 1,25D production during CKD through activation of Cyp24a1 can have severe downstream endocrine effects, including causing hyperparathyroidism and metabolic bone disease." (PMID 35656701, 2022). "This could aggravate the hyperparathyroidism and its consequences on bone mineralization and contribute to the poor performance of individuals with elevated FGF23 concentrations." (PMID 35612845, 2022). "Hyperparathyroidism augments the TmP/GFR lowering effect of FGF23 excess." (PMID 33615106, 2021). "While a PTH increase by a factor of 20–30 may already represent severe, uncontrolled hyperparathyroidism, FGF23 levels over 1,000-fold higher than in healthy controls have been described in CKD." (PMID 30013515, 2018). "After adjusting for serum calcium, phosphate, fibroblast growth factor 23, and use of alfacalcidol, the Bb genotype was a significant predictor of developing both moderate (OR,3.88; 95 CI 1.13–13.25, p = 0.03) and severe hyperparathyroidism(OR, 2.54; 95 CI 1.08–5.96, p = 0.03)." (PMID 29415666, 2018). "Phosphate retention causes hyperparathyroidism and bone disease, and is also a potent vascular toxin in its own right, as well as through its effects on parathyroid hormone (PTH) and fibroblast growth factor 23 (FGF23)." (PMID 25543193, 2015). "High serum levels of calcium may follow from hyperparathyroidism or high serum vitamin D levels which may then suppress production of another hormonal regulator, FGF23, and lead to down-regulation of klotho, a cancer prevention protein." (PMID 23866097, 2013). "Nephrectomized rats had significant uremia, hyperparathyroidism and elevated FGF23." (PMID 24373521, 2013). "Also, as FGF23 lowers PTH gene expression and secretion, inhibiting FGF23 may cause hyperparathyroidism, which can also lead to hypercalcemia and HC." (PMID 39687707, 2024). "However, there is some suggestion that persistent hypophosphataemia beyond 1 year post-transplantation may be driven by hyperparathyroidism, as FGF-23 levels have usually fallen significantly before this point." (PMID 34886802, 2021). "Low levels of vitamin D3 increase Fibroblast growth factor-23 (FGF-23), leading to hyperparathyroidism and bone remodeling." (PMID 40426990, 2025). "Notably, excess fibroblast growth factor-23 (FGF23) coupled with reduced Klotho, as well as skeletal resistance to PTH due to disrupted Wnt–β-catenin signaling (exacerbated by uremia-related intestinal dysbiosis), have all been implicated in maintaining hyperparathyroidism in CKD." (PMID 40725638, 2025). "Six months post-KTx, 6 (32%) patients still present with metabolic acidosis, 10 (53%) persistent hyperparathyroidism (but always < 2 ULN), and 5 (26%) elevated FGF23 levels." (PMID 39384649, 2024). "Further investigations of FGF-23 and PTH interplay should be conducted to elucidate the pathogenesis of hyperparathyroidism and tumorigenesis in some cases of TIO." (PMID 35090436, 2022). "In conclusion, the effect of FGF23 excess on TmP/GFR is altered by PTH such that the effect is ameliorated by hypoparathyroidism and the effect is augmented by hyperparathyroidism." (PMID 33615106, 2021). "Preliminary studies have shown that prolonged anti-FGF23 treatment may stimulate PTH secretion, thus leading to the development of hyperparathyroidism." (PMID 40297189, 2025). "Furthermore, in the clinical situation of hyperparathyroidism in CKD, extremely high levels of FGF23 decrease calcitriol, which in turn increases PTH levels." (PMID 38732094, 2024). "Noteworthy, the aim of the intervention was not directly to influence FGF23 synthesis or release but primarily targeted hyperparathyroidism." (PMID 30013515, 2018).
hyperparathyroidism (continued). "Despite an improvement of hyperparathyroidism, FGF23 did not change renal function and pathology and cardiac mRNA expression of pro-hypertrophic markers including skeletal muscle α-actin, myosin heavy chain (MHC) and atrial natriuretic peptide (ANP)." (PMID 30200452, 2018). "The genetic deletion of Fgf23 in Dmp1KO mice reduced PTH levels by 50%, and 1,25(OH)2D levels were reduced proportionally to PTH levels, suggesting that the increased 1,25(OH)2D levels observed in Dmp1KO mice are mainly driven by persistent hyperparathyroidism." (PMID 37943605, 2023). "A feedback of FGF23 on PTH production may not be present in advanced hyperparathyroidism due to resistance to the action of FGF23." (PMID 30086150, 2018).
endothelial dysfunction (82 papers, 2013 to 2026). In vascular diseases, endothelial dysfunction is a systemic pathological state of the endothelium (the inner lining of blood vessels) and can be broadly defined as an imbalance between vasodilating and vasoconstricting substances produced by (or acting on) the endothelium. "FGF23 stimulates pro-fibrotic factors, induces pro-hypertrophic genes, contributes to endothelial dysfunction, and is associated with inflammatory macrophages." (PMID 40725010, 2025). "Despite its physiological functions, it has been demonstrated that FGF-23 is involved in systemic atherosclerosis via nitric-oxide-associated endothelial dysfunction and calcium-phosphate-related bone mineralization." (PMID 40137447, 2025). "A multivariable regression analysis of CKD patients showed that proteinuria was significantly and independently associated with elevated FGF23 levels when taking blood pressure, endothelial dysfunction, eGRF, and hs-CRP into account." (PMID 40421989, 2025). "Elevated FGF23 and reduced Klotho levels have been linked to arterial stiffness, vascular calcification, and endothelial dysfunction." (PMID 41516280, 2025). "Recent research indicates that FGF23 directly impacts endothelial dysfunction, leading to a predisposition to endovascular diseases, recognized as key contributors to atherosclerosis, a significant hallmark of T2DM." (PMID 39596980, 2024). "Given that phosphorus concentrations drive other disorders associated with increased CV risk (e.g., endothelial dysfunction, vascular calcification, fibroblast growth factor-23, parathyroid hormone), phosphate is a logical target to improve CV health." (PMID 35497793, 2022). "Among CKD patients, biomarkers involved in the pathogenesis of CKD-mineral bone disorder (CKD-MBD), such as phosphorus, parathyroid hormone, and fibroblast growth factor 23, are associated with endothelial dysfunction." (PMID 35903313, 2022). "The first detectable vascular abnormality even in patients with mild CKD is endothelial dysfunction that is associated with oxidative stress, while such a link with FGF23 needs to be proven." (PMID 34536161, 2021). "High levels of FGF23 have been shown to be clinically associated with endothelial dysfunction and arterial stiffness." (PMID 32570781, 2020). "Some recent studies have reported strong association of FGF23 with endothelial dysfunction and cardiovascular risk in CKD subjects." (PMID 30456544, 2019). "Elevated FGF23 predisposes to vascular calcification and is associated with vascular stiffness and endothelial dysfunction in the general population with normal renal function." (PMID 30192823, 2018). "In recent years, recent clinical and experimental studies demonstrated positive associations between endocrine-acting FGF23, cardiac remodeling, and endothelial dysfunction in pathological conditions in humans and rodents." (PMID 29892269, 2018). "Previous clinical studies have shown that elevated circulatory FGF-23 is associated with endothelial dysfunction in CKD patients." (PMID 28463984, 2017). "Given the previously reported association of fibroblast growth factor 23 (FGF-23) with endothelial dysfunction, we also examined changes in the association between FGF-23 levels and the change in FMD following kidney transplantation." (PMID 27770793, 2016). "It is known that higher FGF-23 concentrations are associated with reduced expression of the co-receptor Klotho, as the cause of endothelial dysfunction." (PMID 26462160, 2015). "In the cross-sectional studies, it was reported that serum FGF-23 levels were associated with high atherosclerotic burden, endothelial dysfunction, arterial stiffness and vascular calcification." (PMID 24180481, 2013). "Elevated FGF23 levels are associated with endothelial dysfunction and small vessel disease." (PMID 41426862, 2025).